ENSG00000212191
Synonyms: LOC124900186
Gene: Small nucleolar RNA gene on chromosome 4 (178,685,886 to 178,685,956, reverse strand). Ensembl gene ENSG00000212191.
Gene Ontology:
Biological process: RNA processing
Cellular component: nucleolus
Homologues: Orthologues: rat LOC120099030 (72% identical). Paralogues in human: SNORD65 (80% identical), SNORD65C (79% identical), SNORD65B (73% identical).